CDK8 (cyclin dependent kinase 8)
Diseases named in the same sentence as CDK8 in open-access papers (continued):
Sharing a sentence is not in itself a finding about the gene and the disease.
tumor (continued). "A further layer of complexity was recently added by the finding that the CDK8/cyclin C axis acts in a tumor-suppressive manner in T-cell acute lymphoblastic leukemia (T-ALL)." (PMID 31248103, 2019). "In contrast to most targets of tumor-suppressive drugs (such as, for example, CDK4/6), very few tumor cell lines showed pronounced dependency on CDK8/CDK19/CCNC in DepMap analysis." (PMID 31382571, 2019). "This patient had six verified tumor mutations (ARID1B, ATM, CDK8, FANCA, and two RASA1 mutations), all of which were detected in the preoperative plasma sample." (PMID 30554450, 2019). "To further confirm that miR-770 performed a tumor suppressor function via CDK8, we constructed a CDK8 overexpression vector, which was cotransfected with miR-770 into U251 cells." (PMID 30524203, 2018). "Our work has identified CDK8/19 as a mediator of damage-induced tumor-promoting paracrine activities of both tumor and normal cells; as a consequence, CDK8/19 inhibitors increase the efficacy of chemotherapy in vivo." (PMID 28147342, 2017). "In vivo treatment with a CDK8/19 inhibitor Senexin B suppressed tumor growth and augmented the effects of fulvestrant in ER-positive breast cancer xenografts." (PMID 28147342, 2017). "In contrast, tumour sections from the miR-101-treated mice exhibited only weak expression of cytoplasmic CDK8, β-catenin, and cyclin D1." (PMID 26286725, 2015). "In vivo, Med1, Med14, Med21, and Cdk8 have been shown to be required in hair follicle stem cells, plant meristem, mouse blastocysts, and tumor cells, respectively." (PMID 25772472, 2015). "CDK8 is further required for tumor growth and maintenance of tumor dedifferentiation in vivo and has been reported to play a role in control of cancer and stem cell function." (PMID 25625291, 2015). "Immunohistochemical staining of tumour tissue sections was also performed to detect expression of CDK8, β-catenin, and cyclin D1 in vivo." (PMID 26286725, 2015). "Case 14 was notable in that analysis by IMPACT revealed no mutations in both the beta-catenin and RAS pathways, although the tumor harbored an amplification of CDK8, which has be shown to dysregulate the WNT/beta-catenin pathway." (PMID 25164765, 2014). "For example, the downregulation of the MED-19 subunit of mediator inhibits cell growth and migration in tongue cancer, and CDK8 downregulation induces tumor cell differentiation." (PMID 24576043, 2014). "As predicted, both CDK8 and β-catenin expression level were markedly higher in tumor compared to adjacent normal tissues." (PMID 22104393, 2011). "The expression levels of CDK8 and β-catenin in adjacent normal tissues were lower than in tumor tissues (P < 0.05)." (PMID 22104393, 2011). "As predicted, the expression of CDK8 was also correlated with the expression of β-catenin in both tumor tissues (r = 0.485, P < 0.05) and adjacent normal tissues (r = 0.346, P < 0.05)." (PMID 22104393, 2011). "Results showed that mRNA expression levels of CDK8 and β-catenin in tumor tissues was significantly higher than in adjacent normal tissues (P < 0.05)." (PMID 22104393, 2011). "Herein, we hypothesized that CDK8 activity contributes to the tumor growth of MED12 WT leiomyomas and is influenced by sex steroid hormone kinetics." (PMID 41493967, 2026). "An in-silico study with a molecular modeling approach showed apigetrin, cyanaroside, and cuminum compounds might inhibit CDK8 and PR receptors, indicating potential anti-tumor, anti-proliferative and enzyme inhibitory effects." (PMID 41346617, 2025). "As cell cycle gene CDK8, usually involved in tumor growth, was one of the most potential targets activated by HBV-SITE-1, we performed ChIP-seq and displayed that the H3K27ac peaks were located at about 30 kb upstream of CDK8 promoter, which was verified as active enhancer by ChIP-qPCR." (PMID 40405227, 2025).
tumor (continued). "Inhibition of CDK8/CDK19 was shown to influence gene expression in host stroma of mice harbouring CRPC xenografts and these transcriptional changes were tentatively linked to tumour suppression." (PMID 40163908, 2025). "Additionally, prolonged CDK8/CDK19 inhibition downregulated the MYC pathway leading to tumour regression." (PMID 40163908, 2025). "Altogether, these data suggest that the site-specific tumor inhibitory effect of CDK8 knockdown or inhibition may be related to the environment-specific roles of TIMP3 and MMPs." (PMID 38606172, 2024). "We previously showed the in vivo specificity of tumor suppression by CDK8/19i in other tumor types." (PMID 39541354, 2024). "CDK8 was identified as an essential gene for MB tumor growth." (PMID 39574899, 2024). "In addition to their effects on tumor cells, CDK8/19i suppress tumor-promoting paracrine activities of stromal fibroblasts and stimulate tumor surveillance by NK cells and effector T cells." (PMID 39541354, 2024). "Therefore, the combination of PARP inhibitors and CDK8 inhibitors will also be a new direction for tumor treatment." (PMID 38606172, 2024). "Only 1 of the 3 PDX models, SM0310, showed sufficient tumor take and could be tested for the response to CDK8/19 inhibition in castrated NSG mice." (PMID 38546787, 2024). "In addition to their effects on tumor cells, CDK8/19i were also shown to stimulate tumor surveillance by NK cells and effector T cells." (PMID 38546787, 2024). "Additionally, CDK8 shows promise as a target for augmenting natural killer cell-mediated tumor control." (PMID 38615023, 2024). "Therefore, the dual role of CDK8 in the process of tumor development is worth further exploration and summary." (PMID 38606172, 2024). "In a tumor initiated by xenografts of lung tumor cells of mice, the injection of miR-101 suppressed lung tumor growth, macrophage tumor infiltration, and inflammation and inhibited CDK8 and Ki-67 expression." (PMID 35884901, 2022). "Hence, the useof CDK8/19 inhibitors in the treatment of certain tumor types should beconsidered a super-enhancer- mediated restoration of normal gene expression inmalignant cells." (PMID 33959383, 2021). "CDK8-expressing cells gave rise to increasing Luciferase signals from day 9 to 15 post surgery at the site of injection, indicative of the regrowth of the tumor." (PMID 34689158, 2021). "Inhibition of upstream cyclin-dependent kinase 8 (CDK8) may be a therapeutic strategy for stimulating NK cell-mediated tumor surveillance." (PMID 34017344, 2021). "We found that CDK8 was overexpressed and correlated with poor survival and tumor subtypes in CRC." (PMID 32596239, 2020). "This was in line with a previous study that suggested a tumor promoting role for CDK8 in CRC." (PMID 32596239, 2020). "Reducing CDK8 expression significantly increased the inhibitory effects of 20 Gy on tumor growth." (PMID 32596239, 2020). "Potentially, targeting CDK8 for inhibition, at least in CDK8 over-expressing tumors, could help restore e2f1 activity in these tumors, promoting inhibition or regression of tumor growth." (PMID 32596239, 2020). "The study on Cdk8 has been mainly focused in the field of tumor biology." (PMID 31552016, 2019). "This unique function defines CDK8/19 as mediators of transcriptional reprogramming, a process that plays a key role in the plasticity of tumor cells, allowing these cells to colonize heterologous environment (metastasis) and survive adverse conditions (drug resistance)." (PMID 31717492, 2019). "Functional assays identified a tumor suppressive role for macroH2A1.1 in GC: Cyclin dependent kinase 8 (CDK8) expression analysis and wound healing assays showed that HGC-27 cells over-expressing macroH2A1.1 were less proliferative and invasive than control cells." (PMID 31096699, 2019).
tumor (continued). "Interestingly, while the in vitro growth-inhibitory effect of fulvestrant alone was much stronger than that of Senexin B alone, the in vivo effects of the two compounds were similar, possibly reflecting a role of CDK8/19 in tumor-stromal interactions." (PMID 28147342, 2017). "Also conscious of the potentially opposing context-dependent roles of CDK8 in tumor development, we set out to clarify the therapeutic potential of targeting CDK8/19." (PMID 27935476, 2016). "Due to their potential ability to stabilize Notch, cyclin C/CDK8/19 inhibitors may be of therapeutic benefit for the hematologic malignancies in which Notch functions as a tumor suppressor such as CML and CMML." (PMID 25914884, 2015). "In addition, the expression of CDK8 was correlated with the expression of β-catenin in both tumor tissues (r = 0.744, P < 0.01) and adjacent normal tissues (r = 0.650, P < 0.05)." (PMID 22104393, 2011). "Moreover, the expression of CDK8 was correlated with the expression of β-catenin in both tumor and adjacent normal tissues (P < 0.05)." (PMID 22104393, 2011). "Furthermore, SW480-derived microvesicles are enriched with CENPE, KIF15, CEP55, CCNA2, NEK2, PBK, and CDK8 that are M-phase-related transcripts involved in tumorigenesis and tumor progression." (PMID 19930720, 2009). "Notably, the regulatory effect of OXCT1 on tumor cell migration could be reversed by a CDK8 inhibitor." (PMID 41492470, 2026). "Senexin A is a natural product and the earliest CDK8 inhibitor, which not only inhibits p21-stimulated transcription in vitro and in vivo but also suppresses the production of cytokines from damaged cells and the paracrine activity that damages both tumor and normal cells during chemotherapy." (PMID 38606172, 2024). "However, CDK8 has also been confirmed to be a tumor suppressor, indicating that it not only promotes the development of tumors but may also be involved in tumor suppression." (PMID 38606172, 2024). "This analysis suggested an increase in tumor-associated myocytes that occurred in everolimus-adapted tumors and was counteracted by CDK8/19i, which could reflect changes in tumor invasion of the muscle layer, which was previously shown to be inhibited by CDK8/19i." (PMID 39541354, 2024). "However, CDK8 can also inhibit tumor growth, for instance in the case of endometrial cancer." (PMID 37718413, 2023). "The reason for this could be that the tumor inhibitor miR101 is disturbed in tumor-derived exosomes under hypoxic stress, leading to the upregulation of cyclin-dependent kinase 8 (CDK8) in macrophages and the stimulation of IL1A and IL6 secretion in macrophages." (PMID 36071472, 2022). "We rather hypothesize that CDK8 interferes with NK-cell-mediated tumor surveillance by regulating distinct checkpoints within TNBC cells as our transcriptome analysis revealed differential expression of crucial NK-cell-receptor ligands including the immune checkpoint protein PD-L1." (PMID 34689158, 2021). "Therefore, despite the pro-oncogenic effects associated with Cdk8 overexpression, these observations allude to a tumor suppressive role of cyclin C. This inconsistency may be explained by cell-type specific differences in cyclin C-Cdk8 transcriptional control." (PMID 30621145, 2019). "(In contrast to SERDs, the tumor-suppressive activity of SERMs, such as tamoxifen, involves ER-mediated transcriptional signaling which is modified by this drug, and CDK8/19 inhibition could potentially interfere with the effect of SERMs by suppressing ER signaling)." (PMID 28147342, 2017). "Therefore, cyclin C/CDK3/CDK8/CDK19 complexes function as tumor suppressors in T-ALL by preventing the accumulation of ICN1 and the lack of these complexes led to enhanced T-ALL development in Lck-LMO1 transgenic mice that mimic the alterations found in human T-ALL." (PMID 25914884, 2015).
tumor (continued). "Analysis of CDK8 and CDK19 gene expression in 4,798 normal and 7,843 tumor tissue clinical samples from 16 different organs was conducted using RNA-Seq data in the TNMplot database." (PMID 38546787, 2024). "After 11 days of treatment, CDK8/19i treatment strongly decreased serum PSA levels and moderately but significantly inhibited tumor growth, based on the final tumor weights." (PMID 38546787, 2024). "CDK8/19 inhibitors showed efficacy in patient-derived xenograft models of CRPC, and a gene signature of Mediator kinase activity correlated with tumor progression and overall survival in clinical samples of metastatic CRPC." (PMID 38546787, 2024). "We also measured the effect of Senexin B on the number of circulating tumor cells (CTC) in mouse blood, an early indicator of metastatic spread, and found that the CTC number was strongly reduced by the CDK8/19i." (PMID 39541354, 2024). "Like CDK8/CDK19, CDK12, and CDK13 have been shown to have both tumor‐permissive and suppressive functions." (PMID 37718413, 2023). "Meanwhile, on the TCGA portal, we found that CDK7, CDK8, CDK9, CDK12, CDK19, and CDK20 mRNA levels were differentially expressed in the 4 molecular tumor subtypes." (PMID 33686962, 2021). "Moreover, the down-regulation of miR-107 may cause cell cycle and proliferation due to the up-regulation of CDK6 (also targeted by miR-103) and CDK8 and metastasis and tumor growth because of the up-regulation of BDNF as well as indirect regulating of the P13K/AKT signaling pathway." (PMID 34635059, 2021). "Based on these observations, CDK19 emerged as a promising therapeutic target in different tumor types, leading to the development of small-molecule inhibitors impeding the activity of CDK19 and its paralog CDK8." (PMID 32752128, 2020). "Cdk8 has been reported to attenuate BMP signaling and TGF-β signaling by binding and phosphorylating the linker region of regulatory Smad proteins in tumor cells." (PMID 31552016, 2019). "Inhibition of CDK8/CDK19 by Senexin B or knockdown counteracts the signal rewiring of EMT-promoting factors and tumor cell invasion." (PMID 31248103, 2019). "We have also used cBioPortal to query RNA-Seq data for CDK8, CDK19, and CCNC RNA expression in different tumor types in the TCGA data." (PMID 31382571, 2019). "It remains to be seen if CDK8 and CDK19 regulate hypoxia during development and tumor growth in vivo." (PMID 30693281, 2018). "CDK8 and CDK9 are required for the maintenance of undifferentiated states of tumor embryonic stem cells." (PMID 24576043, 2014). "CDK8 was also reported to regulates the activation of STAT1 and NK cell cytocytoxity in tumor." (PMID 40888963, 2025). "Here, we observed that CDK8 was elevated in all OC, with primary and metastatic OCCC tumor tissues expressing the highest levels of CDK8 compared to non-malignant/benign tissue samples." (PMID 40149277, 2025). "CDK8/19i slowed down tumor growth relative to the control group, with no detrimental effect on mouse body weights." (PMID 38546787, 2024). "In contrast, inhibition of ERK and CDK8/19 delayed the acquisition of resistance, resulting in a 34% reduction in tumor weight at study endpoint without additional toxicity." (PMID 38822082, 2024). "Complete tumor disappearance without recurrence was observed in 25% of animals receiving continuous CDK8/19i treatment." (PMID 38546787, 2024). "In accordance with the unaltered cell proliferation in vitro, we did not observe any significant difference in primary tumor growth and weight irrespective of the expression of CDK8." (PMID 34689158, 2021). "Given the high range of CDK8 expression in tumor samples, it is not surprising that CDK8 RNA levels also showed the best correlations with decreased survival in several tumor types." (PMID 31382571, 2019).
tumor (continued). "A combination of Senexin B (a CDK8/CDK19 inhibitor) with fulvestrant (a selective down-regulator of the estrogen receptor) shows an enhanced tumor-suppressive effect with no apparent toxicity in mouse models." (PMID 31248103, 2019). "While tumor initiation is not affected, tumor growth rate and tumor size are increased upon ablation of CDK8, accompanied by reduced histone H3K27 tri-methylation affecting the promoters of PcG-regulated genes and increasing oncogenic signaling." (PMID 30693281, 2018). "As single agents, however, CDK8/19 kinase inhibitors showed little or no growth-inhibitory effect in the majority of tested tumor and normal cell types." (PMID 28147342, 2017). "For example, CDK8/19 inhibitors might modulate antitumor immunotherapy by inactivating STAT1 and stimulating tumor surveillance by NK cells." (PMID 27935476, 2016). "Additionally, single-agent CDK8/19i treatment led to significant tumor growth inhibition in vivo without any toxicity." (PMID 40149277, 2025). "Hence, the requirement of castration for the effect of CDK8/19i on CRPC is not absolute but depends on the specific tumor." (PMID 38546787, 2024). "The reasons for the slight difference in effects of Cdk8 deletion between chemical carcinogenesis and Apcmin mutation are currently unclear, but, taken together, these studies suffice to conclude that Cdk8 has neither oncogenic nor strong tumour suppressor activity in the mouse intestine." (PMID 36545778, 2023). "Consistent with observations that CDK8 phosphorylation has both positive and negative effects on transcription factors, alterations in the CDK8 and cyclin C (CCNC) genes have been implicated as both oncogenes and tumor suppressors." (PMID 37671866, 2023). "Indeed, the exceptional capacity of hepatic tumor cell lines to support DENV2 replication may lie in their already expanded metabolic activity, which appears to be dependent upon CDK8/19 enzymatic activity." (PMID 32560467, 2020). "Hence, the results of this analysis suggest that growth inhibition of tumor cell lines is not a very productive approach to identifying disease targets for CDK8/19 inhibitors." (PMID 31382571, 2019). "CDK8 may reportedly act both as an oncogene and as a tumor suppressor, but until recently, the absence of a potent and selective inhibitor of CDK8 has restricted many functional studies to genetic inhibition using shRNA or siRNA." (PMID 27935476, 2016). "Therefore, because of the dual role of the cyclin C/CDK8/CDK19 complexes functioning in some tumors as oncogenes and in other tumors as tumor suppressor genes the use of pharmacological inhibitors of this complex should be carefully considered depending on tissue type." (PMID 25914884, 2015). "The role of CDK8/19 in non-genetically acquired antitumor drug resistance has been demonstrated by the ability of selective small-molecule CDK8/19 inhibitors (CDK8/19i) to sensitize tumor cells or to prevent the emergence of resistance to chemotherapeutics including inhibitors of EGFR, HER2 and MEK." (PMID 39955308, 2025). "We investigated the effects of CDK8 and CDK19 expression and kinase activity on in vivo growth of 22Rv1 xenografts, with or without androgen deprivation, by monitoring tumor growth of 22Rv1 derivatives in intact or castrated male NSG mice." (PMID 38546787, 2024). "CDK8/19i suppressed tumor growth in NSG mice, with no detrimental effects on body weight, but MYC-CaP-CR tumor suppression was not as complete in NSG mice as in the immunocompetent FVB." (PMID 38546787, 2024). "However, differentiation in the intestinal epithelium of Cdk8 knockouts was not assessed nor were effects on gene expression in vivo, and the role of CDK8 in restraining intestinal carcinogenesis has not been confirmed using inducible Cre drivers nor other means of tumour induction." (PMID 36545778, 2023). "In the absence of CDK8, the epithelial-to-mesenchymal transition (EMT) is impaired and immune-mediated tumor-cell clearance is facilitated." (PMID 34689158, 2021).
tumor (continued). "Comparable to the kinase-independent role of CDK8 in EMT, enhanced NK-cell-mediated recognition and elimination of E0771 cells was not recapitulated upon inhibitor treatment of the tumor cells." (PMID 34689158, 2021).